PROM2 (prominin 2)
Synonyms: PROML2
Tractability: Antibody: UniProt places it where antibodies can reach, with medium confidence; UniProt predicts a signal peptide or a membrane-spanning region; its Gene Ontology location is reachable by antibodies, with medium confidence; the Human Protein Atlas places it where antibodies can reach.
Gene: Protein-coding gene on chromosome 2 (95,274,444 to 95,302,296, forward strand). Ensembl gene ENSG00000155066.
Subcellular location: Apical cell membrane; Basolateral cell membrane; Cell projection, microvillus membrane; Cell projection, cilium membrane
Subcellular location (Human Protein Atlas): Nucleoplasm; Plasma membrane; Annulus; Cell Junctions; End piece; Mid piece; Principal piece
Gene Ontology:
Molecular function: protein binding; cholesterol binding
Biological process: negative regulation of caveolin-mediated endocytosis; negative regulation of pinocytosis; positive regulation of cell projection organization; positive regulation of protein phosphorylation; regulation of clathrin-dependent endocytosis; regulation of GTPase activity; microvillus organization
Cellular component: cell projection; extracellular exosome; apical plasma membrane; cell surface; cilium; cytoplasmic vesicle; membrane raft; microspike; microvillus; plasma membrane; prominosome; basolateral plasma membrane; ciliary membrane; membrane; microvillus membrane
Genetic constraint (gnomAD): Loss-of-function variants: 88 observed, 101.89 expected, observed/expected ratio (o/e) 0.86, 90% interval 0.73 to 1.03. The upper end of that interval is the gene's LOEUF score, 1.03, which puts it in group 4 of 6, group 1 being the genes least tolerant of losing a copy. Missense variants: 992 observed, 1,026.2 expected, observed/expected ratio (o/e) 0.97, 90% interval 0.92 to 1.02. Synonymous variants: 458 observed, 439.87 expected, observed/expected ratio (o/e) 1.04, 90% interval 0.96 to 1.12.
Homologues: Orthologues: chimpanzee PROM2 (99% identical), macaque PROM2 (93% identical), pig PROM2 (80% identical), dog PROM2 (79% identical), rabbit PROM2 (77% identical), guinea pig PROM2 (76% identical), rat Prom2 (74% identical), mouse Prom2 (73% identical), tropical clawed frog prom2 (33% identical), zebrafish prom2 (28% identical), Caenorhabditis elegans prmn-1 (18% identical), Drosophila melanogaster promL (17% identical), and 1 more. Paralogues in human: PROM1 (25% identical).
Diseases named in the same sentence as PROM2 in open-access papers:
PROM2 is named in the same sentence as 37 diseases in open-access papers, as found by Europe PMC text mining. Sharing a sentence is not in itself a finding about the gene and the disease. The quoted sentences say what the papers report.
breast carcinoma (16 papers, 2020 to 2025). "For instance, low PROM2 expression was associated with poorer relapse-free survival in HER2+ breast cancer patients compared to ER+ and PR+ breast cancer patients." (PMID 31164716, 2020). "Alternatively, prominin 2 (PROM2), a membrane glycoprotein, produces ferroptosis resistance in epithelial and breast cancer cells by promoting exosome-dependent iron export." (PMID 39975561, 2025). "In vitro, PROM2 overexpression has been shown to lead to ferroptosis resistance in breast cancer cell lines." (PMID 38515278, 2024). "Most interestingly, using RNAseq approaches, upregulation of Prom2 has been recognized as a strong survival response against ferroptosis in mammary epithelial and breast carcinoma cells." (PMID 38757782, 2024). "PROM2 is induced by ferroportin, and Prominin2 promotes the ferroptosis resistance of breast cancer cells." (PMID 38152394, 2023). "A prior study proved that prominin 2 participates in ferroptosis resistance in mammary epithelial and breast carcinoma cells by promoting exosome-mediated iron export." (PMID 36117534, 2022). "Alternatively, prominin 2 (a member of the prominin family of pentaspan membrane glycoproteins, PROM2) exports iron by forming ferritin-containing exosomes in epithelial and breast cancer cells, leading to ferroptosis resistance." (PMID 34996454, 2022). "In this regard, studies have shown that PROM2 can promote the proliferation, migration, and invasion of breast cancer by activating the PI3K/AKT pathway." (PMID 35314744, 2022). "In breast carcinoma cells, PROM2 has been found to contribute to iron transportation and inhibits ferroptosis through the formation of ferritin-containing MVBs and exosomes." (PMID 34728613, 2021). "Furthermore, prominin 2 (PROM2) reduces ferroptosis in breast cancer cells by promoting the export of iron from these cells." (PMID 40740786, 2025). "Next, we observed that PROM2 upregulation was associated with poor OS in lung cancer; however, owing to contradictory results, its role in breast cancer was not clear and the receptor status of breast cancer cells also had some effect on patient survival." (PMID 31164716, 2020). "These metabolites can act through intervening in breast cancer targets such as SARM1, RGS5, BAG1, PROM2, and NEAT1." (PMID 40223933, 2025). "Again, we assessed the link between PROM2 expression and ferroptosis resistance in PDX models of renal and breast cancers." (PMID 38515278, 2024). "Therefore, PROM2 expression is not a reliable prognostic marker of OS in patients with breast cancer." (PMID 31164716, 2020). "In contrast, the oncogenic role of PROM2 in lung cancer was obvious, unlike in breast cancer." (PMID 31164716, 2020).
melanoma (7 papers, 2020 to 2025). A malignant, usually aggressive tumor composed of atypical, neoplastic melanocytes. "Overall, our results demonstrated that PROM2 overexpression was directly associated with ferroptosis resistance in human melanoma both in vitro and in vivo." (PMID 38515278, 2024). "In a clinical study using biopsy samples from 101 patients with melanoma lymph node metastases, we demonstrated that high PROM2 expression was associated with a risk of distant lung and brain metastasis and shorter survival." (PMID 38515278, 2024). "Here, for the first time, using melanoma cell lines injected intravenously in mice and patient‐derived melanoma xenografts, we demonstrated that the metastatic burden was linked to PROM2 expression via an EMT phenotype." (PMID 38515278, 2024). "Another major strength of our study is the fact that PROM2 overexpression may not only be associated with metastatic processes in melanoma, but also with other cancer types, including clear‐cell renal cell carcinomas and triple‐negative breast cancers." (PMID 38515278, 2024). "Both in vitro and in vivo, we successively demonstrated that PROM2 overexpression increased invasion and migration, and thus the metastatic process via epithelial‐to‐mesenchymal transition (EMT) activation, and that PROM2 overexpression was associated with ferroptosis resistance in melanoma." (PMID 38515278, 2024). "Melanoma studies identify prominin 2 (PROM2) as maintaining membrane stability through endocytic recycling regulation." (PMID 40919133, 2025). "Overall, the invasive and migration phenotypes linked to PROM2 overexpression, and thus the increased metastatic potential, are associated with an EMT phenotype in melanoma models." (PMID 38515278, 2024). "PROM2 overexpression (A375 PROM2 clone) dramatically increased the metastatic potential of the A375 melanoma cell line with massive lung and pleural metastases, and also heart and muscle metastases." (PMID 38515278, 2024). "In melanoma cells, we found a significant decrease in the amount of Fe2+ when PROM2 expression increased." (PMID 38515278, 2024). "We modulated the expression of PROM2 in the two melanoma cell lines, either by transfection with a plasmid activating PROM2 promoter or a KO plasmid." (PMID 38515278, 2024). "Using an oligonucleotide anti‐sense anti‐PROM2, we efficaciously decreased PROM2 expression and prevented metastases in melanoma xenografts." (PMID 38515278, 2024). "While the EGFR, PROM2 mRNA in melanoma tissue was lowly expressed than that in adjacent normal tissues." (PMID 35692844, 2022). "In a series of 101 melanoma lymph node metastases, using transcriptomic analyses on laser‐microdissected melanoma cells, we identified prominin‐2 (PROM2) as a biomarker predictive of distant metastases and decreased survival, thus providing a promising new bio‐target." (PMID 38515278, 2024). "Thus, based on mRNA expression and clinical data from Oncomine and TCGA, we conclude that PROM1 has as an oncogenic role in brain, esophageal, ovarian, and gastric cancers and melanoma and PROM2 shows oncogenic behavior in lung and ovarian cancers." (PMID 31164716, 2020). "Moreover, several other expression profiling studies have reported that PROM2 is upregulated in various cancers including breast, brain, lung, renal, and tongue cancers and melanoma." (PMID 31164716, 2020). "The expression of PROM2 (prominin 2) is upregulated in kidney cancer and melanoma." (PMID 33490103, 2020). "In the five patient‐derived melanoma xenografts (PDX), we identified two models with a significantly higher PROM2 expression compared with the three other models (XM1 and XM2)." (PMID 38515278, 2024). "The genes of HAMP, SLC7A5, CYBB, and IFNG were highly expressed in melanoma cell lines, while JDP2, TUBE1, PROM2, GPX2, FBXW7, and ARNTL were lowly expressed in melanoma cell lines." (PMID 35373463, 2022).
melanoma (continued). "The results indicated that high expression of PROM2, EGFR, AURKA, and low expression of IFNG, ARNTL, FBXW7 correlated with a poor prognosis of melanoma patients." (PMID 35692844, 2022). "In the five patient‐derived melanoma xenografts, a negative correlation was also found between PROM2 mRNA expression and lipid peroxidation." (PMID 38515278, 2024). "Overall, PROM2 expression level has an impact in vitro and in vivo on melanoma invasion and migration, but not on cell proliferation." (PMID 38515278, 2024). "In parallel, we quantified Fe2+ in the five patient‐derived melanoma xenografts (total of 25 tumours) and found a significantly lower level of Fe2+ in XM1 and XM2 compared with the other three models, inversely correlated with PROM2 mRNA expression levels." (PMID 38515278, 2024). "The level of PROM2 expression did not influence cell proliferation, whatever the melanoma cell line, neither in vitro, nor in vivo." (PMID 38515278, 2024). "Since CAV1 mRNA and protein overexpression can induce EMT marker overexpression in various cancer cell lines, CAV1, that participates to caveolar endocytosis, could be intermediate between PROM2 and EMT markers in our in vitro and in vivo melanoma models." (PMID 38515278, 2024).
lung carcinoma (6 papers, 2020 to 2024). "High PROM2 mRNA expression has also been associated with shorter survival among patients with metastatic pancreas, renal, ovarian and lung cancers." (PMID 38515278, 2024). "Additionally, PROM2 overexpression is associated with poor overall survival in lung cancer." (PMID 38132167, 2023). "Consistently, PROM2 expression was significantly enhanced in lung cancer cells (NCI-H1650, A549, NCI-H1299, PC-9) compared to BEAS-2B, especially in PC-9 and A549 cells." (PMID 37665741, 2023). "In vivo experiments confirmed that knockdown of PROM2 enhances the sensitivity of lung cancer cells to cisplatin, thereby inhibiting tumor growth." (PMID 37665741, 2023). "More importantly, we demonstrated that PROM2 promoted the proliferation, migration and invasion of lung cancer cells, and inhibited the apoptosis, and their sensitivity to cisplatin in vitro." (PMID 37665741, 2023). "A whole-genome expression profiling study reported that PROM2 is overexpressed in endothelial cells in lung cancer." (PMID 31164716, 2020). "In contrast, our analysis showed that PROM2 is overexpressed in breast and lung cancers, and this result is in agreement with those of previous genome profiling studies and studies on expressed sequence tag (EST) clones deposited in the GenBank database." (PMID 31164716, 2020). "PROM2 has also been demonstrated to be upregulated in subtypes of lung cancer and chromophobe renal cell carcinoma." (PMID 32123287, 2020). "In addition, other studies have shown PROM2 is upregulated in lung cancer and chromophobe renal cell carcinoma." (PMID 32123287, 2020). "Notably, PROM2 expression was increased in lung cancer tissues." (PMID 37665741, 2023). "In contrast, PROM2 was significantly co-expressed with LAD1, C1ORF106, PVRL4, and KCNK5 in lung cancer." (PMID 31164716, 2020).
bladder cancer (5 papers, 2021 to 2025). "Lnc RP11-89 sponges miR-129-5p, upregulating PROM2 and inhibiting ferroptosis in bladder cancer cells." (PMID 40191204, 2025). "Fortunately, a recent report has pointed out that activated PROM2 serves as a tumorigenic regulator in bladder cancer via attenuating ferroptosis." (PMID 37665741, 2023). "For example, lncRNA RP11-89 facilitates tumorigenesis and ferroptosis resistance through PROM2-activated iron export by sponging miR-129-5p in bladder cancer." (PMID 36175889, 2022). "MiR-129-5p targets and represses PROM2 to inhibit iron export, eventually promoting ferroptosis in non-small-cell lung cancer, whereas lncRP11-89 inhibits miR-129-5p to increase PROM2 expression, leading to the suppression of ferroptosis in bladder cancer." (PMID 37686142, 2023). "In this research, we demonstrated that lncRNA RP11-89 could play a regulatory role in bladder cancer ferroptosis and progression directly via a novel ceRNA network of RP11-89/miR-129-5p/PROM2 axis." (PMID 34728613, 2021).
ovarian carcinoma (3 papers, 2020 to 2023). A malignant neoplasm originating from the surface ovarian epithelium. "We observed that PROM1 was frequently overexpressed in esophageal, liver, and ovarian cancers and its expression was negatively associated with prognosis, whereas PROM2 overexpression was associated with poor overall survival in lung and ovarian cancers." (PMID 31164716, 2020). "Third, when compared to that in normal tissues, PROM2 was significantly overexpressed in breast, lung, bone marrow, and ovarian cancers, whereas it was underexpressed in colon, esophageal, gastric, kidney, prostate, and skin cancers." (PMID 37521469, 2023). "Previous studies suggested the potential for PROM2 as a tumorigenic biomarker for lung and ovarian cancers." (PMID 34728613, 2021). "Based on this expression pattern, we performed a multivariate survival analysis of PROM1/PROM2 co-expression in ovarian cancer." (PMID 31164716, 2020). "In contrast, PROM2 was upregulated in myeloma and breast, lung, and ovarian cancers and downregulated in colon, esophageal, gastric, kidney, and prostate cancers." (PMID 31164716, 2020). "In ovarian cancer, PROM2 is slightly co-expressed with CARD14." (PMID 31164716, 2020).
colorectal cancer (2 papers, 2023 to 2025). A primary or metastatic malignant neoplasm that affects the colon or rectum. "In our sensitive HCT116 WT and GPX4 KO mutated cell lines, the lack of PROM2 expression at the mRNA level may result from the sensitivity of colorectal cancer cell lines to ferroptotic cell death, similar to previously reported findings." (PMID 38139836, 2023). "The colorectal cancer HCT116 cell line was found to be sensitive to ferroptosis cell death, with a silenced PROM2 gene." (PMID 38139836, 2023). "Weak negative correlations for PROM2 in tissue data for colorectal cancer confirmed the hypothesis of the sensitivity of colorectal cancer cell lines." (PMID 38139836, 2023).
gastric cancer (2 papers, 2020 to 2023). A primary or metastatic malignant neoplasm involving the stomach. "At the same time, analysis of ferroptosis-related genes associated normal tissue and gastric cancer tissues screened out 19 FerDEGs: ten of them, i.e., TLR4, KRAS, HSF1, was highly expressed and nine of them, i.e., MUC1, PROM2, MT1G, were lowly expressed in tumor tissues." (PMID 36936437, 2023).
kidney cancer (2 papers, 2020). Primary or metastatic malignant neoplasm involving the kidney. "Meanwhile, both PROM1 and PROM2 are potential targets for skin and kidney cancers." (PMID 31164716, 2020).
non-small cell lung carcinoma (2 papers, 2023 to 2024). A group of at least three distinct histological types of lung cancer, including non-small cell squamous cell carcinoma, adenocarcinoma, and large cell carcinoma. "Furthermore, miR-129-5p targets and downregulates PROM2, inhibiting iron efflux and enhancing ferroptosis in non-small cell lung cancer (NSCLC)." (PMID 39763590, 2024).